SAFB (scaffold attachment factor B)
Description:
Binds to scaffold/matrix attachment region (S/MAR) DNA and forms a molecular assembly point to allow the formation of a 'transcriptosomal' complex (consisting of SR proteins and RNA polymerase II) coupling transcription and RNA processing. Functions as an estrogen receptor corepressor and can also bind to the HSP27 promoter and decrease its transcription. Thereby acts as a negative regulator of cell proliferation. When associated with RBMX, binds to and stimulates transcription from the SREBF1 promoter (By similarity).
Synonyms: SAF-B; SAF-B1; HAP; HET; SAFB1; SAB-B1
Tractability: PROTAC: UniProt records ubiquitination sites on it; ubiquitination databases record sites on it; its protein half-life has been measured.
Gene: Protein-coding gene on chromosome 19 (5,623,035 to 5,668,478, forward strand). Ensembl gene ENSG00000160633.
Subcellular location: Nucleus
Subcellular location (Human Protein Atlas): Nucleoplasm; Midbody
Pathways (Reactome):
Metabolism of proteins: SUMOylation of transcription cofactors
Gene Ontology:
Molecular function: protein binding; RNA binding; chromatin binding; double-stranded DNA binding; RNA polymerase II cis-regulatory region sequence-specific DNA binding; sequence-specific DNA binding; nucleic acid binding
Biological process: chromatin organization; estrogen receptor signaling pathway; positive regulation of transcription by RNA polymerase II
Cellular component: midbody; nucleoplasm; nucleus
Genetic constraint (gnomAD): Loss-of-function variants: 8 observed, 65.78 expected, observed/expected ratio (o/e) 0.12, 90% interval 0.07 to 0.22. The upper end of that interval is the gene's LOEUF score, 0.22, which puts it in group 1 of 6, group 1 being the genes least tolerant of losing a copy. Missense variants: 701 observed, 871.55 expected, observed/expected ratio (o/e) 0.8, 90% interval 0.75 to 0.86. Synonymous variants: 343 observed, 325.42 expected, observed/expected ratio (o/e) 1.05, 90% interval 0.96 to 1.15.
Homologues: Orthologues: macaque SAFB (99% identical), chimpanzee SAFB (98% identical), pig SAFB (93% identical), dog SAFB (93% identical), guinea pig SAFB (90% identical), mouse Safb (86% identical), rat Safb (81% identical), rabbit SAFB (68% identical), tropical clawed frog safb (47% identical), zebrafish safb (42% identical), Drosophila melanogaster Saf-B (28% identical), Caenorhabditis elegans phm-2 (24% identical). Paralogues in human: SAFB2 (73% identical), SLTM (38% identical).
Diseases named in the same sentence as SAFB in open-access papers:
SAFB is named in the same sentence as 36 diseases in open-access papers, as found by Europe PMC text mining. Sharing a sentence is not in itself a finding about the gene and the disease. The quoted sentences say what the papers report.
breast carcinoma (10 papers, 2001 to 2023). "Scaffold Attachment Factor B1 (SAFB1) is a multifunctional protein which has been implicated in breast cancer previously." (PMID 19267898, 2009). "Low SAFB protein levels were also suggested as possible predictors of poor prognosis of breast cancer." (PMID 26482227, 2015). "The scaffold attachment factor B1 and B2 genes, SAFB1/SAFB2 (both located on chromosome 19p13.3) have recently been suggested as tumour suppressor genes involved in breast cancer development." (PMID 19077293, 2008). "Overall, these data suggest that SAFB might serve as a protective role for various cancers, including colorectal cancer, breast cancer, and PAAD." (PMID 34490033, 2021). "The observed loss of SAFB1 in both breast cancer cell lines does not have an effect on ITGB4 mRNA expression whereas loss of SAFB2 and both SAFB proteins significantly increased ITGB4 expression." (PMID 26273616, 2015). "Since it has become clear that many steroid receptor cofactors play important roles in breast tumorigenesis, we investigated whether SAFB could also be involved in breast cancer." (PMID 11207044, 2001). "SAFB (scaffold attachment factor B) belongs to the nuclear matrix family of proteins and low‐protein expression is significantly associated with worse overall survival in breast cancer patients who did not receive adjuvant therapy." (PMID 32536039, 2020). "Using RNAi, we also show, for the first time, that single depletion of either SAFB1 or SAFB2 leads to an increase in expression of the other SAFB protein in both MCF-7 and MDA-MD231 breast cancer cells." (PMID 26273616, 2015). "In addition, low SAFB expression was also predictive of poorer prognosis in patients with breast cancer without adjuvant therapy." (PMID 34490033, 2021).
colorectal cancer (4 papers, 2020 to 2022). A primary or metastatic malignant neoplasm that affects the colon or rectum. "Similar to this, SAFB slowed the development of colorectal cancer by concentrating on the TAK1 promoter’s initial E-box." (PMID 36462498, 2022). "SAFB expression is high in normal colorectal tissues and is low in colorectal cancer, and this low expression of SAFB predicted a worse outcome for patients with colorectal cancer." (PMID 34490033, 2021). "Besides, SAFB was reported to be downregulated in colorectal cancer by COPA analysis, which sustained the NF-κB Pathway during the progression of colorectal cancer." (PMID 31897234, 2020).
Huntington disease (2 papers, 2020 to 2024). Huntington disease (HD) is a rare neurodegenerative disorder of the central nervous system characterized by unwanted choreatic movements, behavioral and psychiatric disturbances and dementia. "Aberrant expression of SAFB has been documented in the nerve cells of brain regions affected by spinocerebellar ataxias (SCAs) and Huntington’s disease (HD), where it is associated with specific polyglutamine expansion pathology." (PMID 39115871, 2024).
neuroblastoma (2 papers, 2020 to 2024). Neuroblastoma (NB) is the most common solid, extracranial childhood tumor. "To assess Drosha binding to the SAFB-ΔRE protein, we tagged the mutant and WT SAFB variants with HA tags to distinguish them from endogenous protein, expressed these in neuroblastoma cells (N2A), and performed a Drosha co-IP followed by anti-HA immunoblot." (PMID 38722021, 2024).
Obesity (2 papers, 2018 to 2021). Accumulation of substantial excess body fat. "Apart from binding to its own mRNA, PABP also binds to ‘A’ rich sequence present within the 5′ UTR of scaffold attachment Factor B (Safb), a protein associated with cell and tumor growth, metabolism and obesity." (PMID 29590218, 2018).
clear cell renal cell carcinoma (1 paper, 2022). "In clear cell renal cell carcinoma, our data convincingly demonstrated a mechanism by which SKA1 promotes tumor metastasis through SAFB-mediated transcriptional repression of DUSP6." (PMID 36462498, 2022).
Intestinal tumors (1 paper, 2022). "This evidence corroborated our result showing that the high activity of the SAFB regulon in Intestinal tumors was strongly associated (p-value << 0.001) with a better prognosis (OS HR 0.78, DSS HR 0.73 and PFI HR 0.78)." (PMID 36230884, 2022).
lymphoma (1 paper, 2024). A malignant (clonal) proliferation of B- lymphocytes or T- lymphocytes which involves the lymph nodes, bone marrow and/or extranodal sites. "Specifically, MYC overexpression in lymphoma increases SUMO2/3-conjugated SAFB (scaffold attachment factor B), a transcriptional corepressor that inhibits MHC-I gene expression." (PMID 38280996, 2024).
melanoma (1 paper, 2026). A malignant, usually aggressive tumor composed of atypical, neoplastic melanocytes. "First, CRISPR activation screens in melanoma cells identify functionally diverse regulators of TCR-specific cytotoxicity, including SAFB, KHDRBS1, MYC, CD44, WNT3A, WNT1 and others." (PMID 41946842, 2026).
pancreatic tumor (1 paper, 2021). "SAFB might improve clinical outcomes via the migration of CD4+ T cells into the pancreatic tumor microenvironment." (PMID 34490033, 2021).
retinoblastoma (1 paper, 2012). A malignant tumor that originates in the nuclear layer of the retina. "We also found that Zbed4 interacts in Y79 retinoblastoma cells with nuclear and cytoplasmic proteins Scaffold Attachment Factor B1 (SAFB1), estrogen receptor alpha (ERα), and cellular myosin 9 (MYH9), as shown with immunoprecipitation and mass spectrometry studies as well as gel overlay assays." (PMID 22693546, 2012). "We also found that Zbed4 interacts with nuclear and cytoplasmic proteins and corroborated these results by co-immunoprecipitating Zbed4 from Y79 retinoblastoma cells with the identified proteins, Scaffold Attachment Factor B1 (SAFB1), Estrogen Receptor alpha (ERα) and cellular Myosin 9 (MYH9)." (PMID 22693546, 2012).
tauopathies (1 paper, 2025). "Overall, RBPs enriched in disease-associated modules included the previously validated CHD4, MACROH2A1, SAFB, WDR82, and PAPOLA proteins, highlighting their potential relevance to tauopathies." (PMID 41205924, 2025).
cancer (15 papers, 2007 to 2024). A tumor composed of atypical neoplastic, often pleomorphic cells that invade other tissues. "Loss of the MHC-I APM is a frequent cause of resistance to cancer immunotherapies, and the pharmacological inhibition of SUMOylation (SUMOi) resulted in reduced activity of the transcriptional repressor scaffold attachment factor B (SAFB) and induction of the MHC-I APM." (PMID 35499080, 2022). "Taken together, these data corroborate that SKA1 physically interplays with SAFB, which induces SAFB-dependent transrepression of DUSP6, consequently promoting cancer aggressiveness." (PMID 36462498, 2022). "Collectively, our data attest that SKA1 physically interacts with the SAFB and impels transcriptional repression of DUSP6, consequently provoking cancer aggressiveness." (PMID 36462498, 2022). "Down-regulated genes such as MMP2, MAPK1, TBFRS7, REL A, SAFB, FES identified GO terms listed as TGF-beta signaling, angiogenesis, IL-4 signaling, cartilage development and cancer-related pathways." (PMID 24756038, 2014). "Likewise, we could not detect any effect on the transcript abundance of SAFB, and MYC protein expression correlated with SAFB protein but not with SAFB mRNA across a large panel of cancer cells lines from the CCLE." (PMID 35499080, 2022).
tumor (8 papers, 2008 to 2022). "We intensively studied the expression pattern of SAFB between tumor and non-tumor tissues based on the TCGA and GTEx databases." (PMID 34490033, 2021). "In comparison, our experience was that tumor areas displayed a higher heterogeneity of SAFB than the morphologically intact (benign) epithelium." (PMID 28915670, 2017). "Compared with non-tumor tissues, SAFB mRNA was significantly lower in PAAD." (PMID 34490033, 2021). "After a strand of screening tests, the scaffold attachment factor B (SAFB) was identified as an independent predictor of outcome and was correlated with the tumor immune microenvironment." (PMID 34490033, 2021).
neurologic disease (4 papers, 2015 to 2026). "In motor neurons from non-neurologic disease control subjects, RBM45 immunoreactivity was largely nucleolar (arrowheads) and SAFB and TDP-43 immunoreactivity was diffuse." (PMID 32586379, 2020). "We first performed immunohistochemistry for RBM45, SAFB, and TDP-43 in the dentate gyrus of non-neurological disease controls, FTLD-TDP, ALS, and AD." (PMID 32586379, 2020). "Elucidating the interaction mechanism between FAM20C and ADAR, SAFB and DAGLA holds crucial implications for understanding both the physiological roles of FAM20C in the nervous system and its pathological contributions to neurological disorders." (PMID 40511628, 2026). "Critically, this was not due to a general decrease in SAFB immunoreactivity, as neighboring cells without RBM45 nuclear inclusions showed strong SAFB immunoreactivity comparable to non-neurologic disease controls (inset)." (PMID 32586379, 2020).
SAFB also shares sentences with these, for which no sentence is quoted: breast tumor (3 papers); Infertility (3); infection (2); invasive breast carcinoma (2); spinocerebellar ataxia (2); alopecia (1); B-cell lymphoma (1); dwarfism (1); epilepsy (1); female subfertility (1); fibrosis (1); hypopituitarism (1); male infertility (1); multiple myeloma (1); multiple sclerosis (1); neurodegenerative disease (1); Parkinson disease (1); Parkinson’s (1); renal carcinoma (1); Rett syndrome (1); schizophrenia (1).